PARP1 (poly(ADP-ribose) polymerase 1)
Diseases named in the same sentence as PARP1 in open-access papers (continued):
Sharing a sentence is not in itself a finding about the gene and the disease.
skin cancer (9 papers, 2018 to 2024). "Preclinical studies have demonstrated a link between PARP1 and angiogenesis, with PARP1-knockout in mouse models of skin cancer resulting in decreased HIF-1α and consequently reduced angiogenesis." (PMID 37430137, 2023). "On the whole, the efficient removal of UV-induced photolesions requires PARP-1, which is consistent with the observation that impaired PARP-1 function increases UV-induced skin cancer in mice." (PMID 33922595, 2021). "In previous reports we showed that PARP-1 inhibition had a higher protection in lymphocytes from skin cancer patients compared to those of AD patients, with control lymphocytes showing intermediate values." (PMID 29472838, 2018). "PARP1 may be associated with xeroderma pigmentosum, complementation group A through interactions with XPA, and the related susceptibility to skin cancer." (PMID 34220964, 2021). "In one study, microarray analysis was conducted on PARP-1 gene expression in over 8000 tumor samples, revealing higher expression levels of PARP-1 in breast, ovarian, endometrial, lung and skin cancers compared to equivalent amounts of normal tissues." (PMID 38392321, 2024).
acute lymphoblastic leukemia (8 papers, 2013 to 2023). Leukemia with an acute onset, characterized by the presence of lymphoblasts in the bone marrow and the peripheral blood. "Indeed, GB elicited an increase of TNF-α production, caspase-8 and caspase-3 activation, and PARP-1 cleavage within pre-B acute lymphoblastic leukemia Nalm-6 cells." (PMID 24039967, 2013). "AML and acute lymphoblastic leukemia (ALL) have been both reported to have genomic alternations of PARP1 and compromised DNA-damage-response gene pathways." (PMID 35327610, 2022). "Autophagy, which is facilitated by cAMP-induced Poly [ADP-ribose] polymerase 1 (PARP1) activation, may help cure acute lymphoblastic leukemia." (PMID 35805104, 2022).
B-cell lymphoma (8 papers, 2010 to 2025). "Researchers have reported a direct interaction between BCL-2 and the enzyme PARP1 in the nuclei of B-cell lymphoma cells, which suppresses PARP1 enzymatic activity, thereby hampering DNA repair." (PMID 37686461, 2023). "Using a chicken B cell lymphoma cell line because it has only a single PARP isoform and constitutively mutates its antibody genes, we compared the types of mutations accumulated in PARP-1−/− cells to wild type." (PMID 20652015, 2010). "Furthermore, genes like CDK7, NRF2, and PARP1 are established chemoresistance markers for various therapies in B-cell lymphoma." (PMID 36058921, 2022). "PARP1 and PARP2 exert opposing effects in c‐Myc‐driven B‐cell lymphoma." (PMID 40904702, 2025). "Previous studies have determined that mice deficient for PARP-1 have increased levels of Tregs, which may have contributed at least in part to the acceleration of tumourigenesis in the absence of PARP-1 in a c-Myc-driven B cell lymphoma mouse model." (PMID 34885119, 2021).
esophageal squamous cell carcinoma (8 papers, 2015 to 2025). Esophageal squamous cell carcinoma (ESCC) is a type of esophageal carcinoma (EC) that can affect any part of the esophagus, but is usually located in the upper or middle third. "This study aimed to assess whether polymorphisms of PARP1 gene could be used as predictive biomarkers for the survival of esophageal squamous cell carcinoma (ESCC) patients from Cixian high-incidence region in northern China." (PMID 33112558, 2020). "Overall, our study indicates that m6A‐modified LNCAROD confers radioresistance of esophageal squamous cell carcinoma through stabilising PARP1, thus providing a new perspective and clue to alleviate radioresistance." (PMID 39367700, 2024). "In this study, we report the poly ADP‐ribosylation (PARylation) of HMGA1 during DNA damage, leading to desensitization of esophageal squamous cell carcinoma (ESCC) cells to the poly(ADP‐ribose) polymerase 1 (PARP1) inhibitor, olaparib." (PMID 39690136, 2024). "To date, no study has been conducted to assess whether PARP1 rs1136410 and rs8679 SNPs, two potentially functional sites, are useful biomarkers to predict the survival of esophageal squamous cell carcinoma (ESCC) patients in Cixian high-incidence region." (PMID 33112558, 2020).
head and neck cancer (8 papers, 2012 to 2025). A primary or metastatic malignant neoplasm affecting the head and neck. "In UT-SCC5 and SAS head and neck cancer cells, PARP1 has been shown to serve as a mediator of EGFR/MEK-dependent regulation of DNA double-strand breaks." (PMID 32093123, 2020). "In preclinical animal models of head and neck cancer, optical imaging agents targeted against αvβ3 integrin, cathepsine B, metalloproteinases, PARP1, and EGFR have been investigated." (PMID 28039488, 2017). "In vitro and in vivo studies have shown that the combination of curcumin and resveratrol enhances the apoptotic effects of head and neck cancer cells, including upregulation of PARP-1 cleavage and the Bax/Bcl-2 ratio and downregulation of ERK1 and ERK2 phosphorylation." (PMID 36193082, 2022).
Nephropathy (8 papers, 2016 to 2025). A nonspecific term referring to disease or damage of the kidneys. "PARP1 hyper-activation is associated with many various characteristics of early nephropathy related to type 1 diabetes, which provides a theoretical basis for developing and studying PARP1 inhibitors and PARP1 inhibitor-containing combination therapies." (PMID 35806303, 2022). "Calcitriol is a potential PARP1 inhibitor in macrophage cell lines, and the association of vitamin D and PARP1 occurs in diabetic cardiomyopathy and nephropathy models." (PMID 34393753, 2021). "Previous research highlights the significance of PARP-1 activity in proximal renal tubular cells in kidney disease." (PMID 39744164, 2025). "Parp1 deficiency protects AagTg mice against MMS-induced tissue damage in the cerebellum, pancreas, spleen and retina, but enhances MMS-induced kidney damage." (PMID 27391435, 2016). "2‐PY is a major NAD+ metabolite that increases with age and illness and has been recognized as a uremic toxin in patients with kidney disease that may exert toxic effects on the tissues and inhibit PARP‐1 activity." (PMID 39354697, 2024). "For example, INO1001, a highly potent PARP1 inhibitor, could prevent oxidative stress and improve nephropathy in diabetic mice and relieve aging-associated cardiac and vascular dysfunction." (PMID 35178387, 2022). "Since previous studies demonstrated that necrosis in females with Immune mediated nephropathy was occurring independently of PARP1, we hypothesized that RIPK3-driven pathways may instead mediate necrosis in this setting." (PMID 27669412, 2016). "Our laboratory has previous shown that male mice lacking PARP1 develop less renal disease during NTS-nephritis than WT mice." (PMID 27669412, 2016).
pulmonary fibrosis (8 papers, 2011 to 2024). Chronic progressive interstitial lung disorder characterized by the replacement of the lung tissue by connective tissue, leading to progressive dyspnea, respiratory failure, or right heart failure. "In contrast, PARP-1-deficient mice exhibited reduced pulmonary fibrosis in response to bleomycin-induced lung injury, relative to wild-type controls." (PMID 36421478, 2022). "Apart from cardiovascular diseases, deficiency of PARP1 can also alleviate pulmonary fibrosis, while PARP1 overactivation can lead to hepatic fibrosis." (PMID 34124031, 2021). "PARP-1 deficient mice exhibited reduced lung fibrosis in response to bleomycin treatment compared to wild-type controls." (PMID 31164820, 2019). "In this part, we summarize the reported scaffolding proteins linked to pulmonary fibrosis, XRCC1 and PARP-1." (PMID 36421478, 2022). "In conclusion, PARP-1 is involved in pulmonary fibrosis by inducing lung fibroblast activation and increasing the expression of α-SMA." (PMID 36421478, 2022). "The aim of the study was to evaluate the cross-talk between PARP-1 and H4R in a model of bleomycin-induced lung fibrosis in PARP-1−/− and WT mice." (PMID 31164820, 2019). "For this purpose, we evaluated the effects of the H4R-selective antagonist, JNJ7777120, and of the H4R agonist, VUF8430, in an in vivo model of bleomycin-induced lung fibrosis, in PARP-1 knock-out and in wild-type mice." (PMID 31164820, 2019). "PARP-1 activity contributes to lung fibroblast activation and induces their proliferation with increased expression of αSMA, which plays a pivotal role in lung fibrosis." (PMID 31164820, 2019). "Our results show that PARylation is essential for the pathogenesis of pulmonary fibrosis and propose that PARP-1 and H4Rs are both involved in inflammatory and fibrotic responses." (PMID 31164820, 2019). "Overall, these findings suggest that PARylation is a key factor for the pathogenesis of pulmonary fibrosis and provide evidence that PARP-1 and H4R are independently involved in the signaling pathways activated during inflammatory and fibrotic processes." (PMID 31164820, 2019). "Briefly, we demonstrate that JNJ, a selective antagonist of the histamine H4R, exerts its anti-inflammatory and anti-fibrotic properties independently of PARP-1 signaling pathway, in an in vivo mouse model of bleomycin-induced lung fibrosis." (PMID 31164820, 2019). "In this study, we investigated the effects of HYDAMTIQ, a potent PARP‐1 inhibitor, in a murine model of lung fibrosis." (PMID 27704718, 2017). "Recently, it has been shown that PARP‐1 activity is required to allow lung fibroblasts activation and proliferation with increased expression of αSMA, which seems to play a major role in lung fibrosis." (PMID 27704718, 2017). "Thus, our results indicate that H4R antagonists can ameliorate lung fibrosis independently of PARP-1 expression." (PMID 31164820, 2019). "Moreover, recent studies demonstrated that genetic depletion and pharmacological inhibition of PARP-1 reduced pulmonary fibrosis in an animal model of bleomycin-induced lung injury, suggesting that PARylation is important for myofibroblast differentiation and for the pathogenesis of the disease." (PMID 31164820, 2019). "HYDAMTIQ, a selective PARP-1 inhibitor, down-regulated the expression of TGF-β and p-Smad3, and thus exhibited an anti-fibrotic effect in bleomycin-induced lung fibrosis." (PMID 28423499, 2017). "In this study, we showed that the beneficial effects of H4R antagonists in reducing progressive pulmonary fibrosis are not dependent upon PARP-1." (PMID 31164820, 2019).
pulmonary fibrosis (continued). "Unlike OGG1, PARP1 exhibits its consistent mechanism in pulmonary fibrosis, that is, PARP-1 inhibition may be significant." (PMID 36421478, 2022). "In conclusion, the therapeutic potential of the combination of H4R antagonists with non-toxic doses of selective PARP-1 inhibitors could significantly reduce the development of pulmonary fibrosis." (PMID 31164820, 2019). "Therefore, selective inhibition of H4Rs together with non-toxic doses of selective PARP-1 inhibitors could have clinical relevance for the treatment of idiopathic pulmonary fibrosis." (PMID 31164820, 2019).
soft tissue sarcoma (8 papers, 2016 to 2021). A malignant neoplasm arising from muscle tissue, adipose tissue, blood vessels, fibrous tissue, or other supportive tissues excluding the bones. "PARP1 had shown predictive and prognostic values in bone and soft tissue sarcomas." (PMID 33142760, 2020). "The expression status of PARP1, γH2AX, BRCA1, and BRCA2 according to the histological type of soft-tissue sarcoma." (PMID 27643881, 2016). "Kaplan-Meier survival analysis with Log-rank test according to the expressions of PARP1, γH2AX, BRCA1, and BRCA2 in various histological types of soft-tissue sarcomas." (PMID 27643881, 2016). "In this study, we evaluated the immunohistochemical expression of PARP1, γH2AX, BRCA1, and BRCA2 and their prognostic significance in 112 cases of soft tissue sarcoma (STS)." (PMID 27643881, 2016). "Univariate Cox proportional hazards regression analysis for survival in various subgroups of soft-tissue sarcomas according to the expression of BRCA1, BRCA2, PARP1, and γH2AX." (PMID 27643881, 2016). "The correlation between the clinicopathological variables and the expression of PARP1, γH2AX, BRCA1, and BRCA2 in soft tissue sarcomas." (PMID 27643881, 2016). "High PARP-1 expression alone and in combination with the expression of other DNA repair molecules (γH2AX, BRCA1, and BRCA2) is prognostic factor for shorter survival in soft tissue sarcoma patients." (PMID 33572586, 2021).
acute promyelocytic leukemia (7 papers, 2010 to 2017). An aggressive form of acute myeloid leukemia (AML), characterized by arrest of leukocyte differentiation at the promyelocyte stage, due to a specific chromosomal translocation t(15;17) in myeloid cells. "In a previous study, we demonstrated that fucoidan induced apoptosis through a caspase-dependent mechanism and further inactivation of PARP-1 in acute promyelocytic leukemia NB4 and HL60 cell lines." (PMID 27329592, 2016). "Poly (ADP-ribosyl)ation of PARP-1 following DNA breaks changes PARP-1 targeting from caspase-3 from caspase-7 in human promyelocytic leukemia cells (HL-60) treated with etoposide phosphate (VP-16)." (PMID 21176168, 2010). "Increased levels of vitamin D appear to down-regulate PARP-1 expression; PARP-1 levels decrease following calcitriol treatment in NB4 cells, which are acute promyelocytic leukemia cells." (PMID 23570271, 2013). "In addition, increased levels of vitamin D seem to down-regulate PARP-1 expression; PARP-1 levels decrease following calcitriol treatment in NB4 cells, which are acute promyelocytic leukemia cells." (PMID 23800102, 2013). "In addition, increased levels of vitamin D seem to downregulate PARP-1 expression; PARP-1 levels decrease following calcitriol treatment in NB4 cells, which represent an acute promyelocytic leukemia cells." (PMID 22619734, 2012).
anemia (7 papers, 2020 to 2025). A reduction in the number of red blood cells, the amount of hemoglobin, and/or the volume of packed red blood cells. "In addition to PARP-1, a critical role in developing hematologic adverse events, particularly anemia, is attributed to PARP-2, as its inhibition has been linked to chronic anemia in animal models." (PMID 40804462, 2025). "Toxic central anemia is well described, as erythropoiesis is normally sustained by PARP1 activation and is also activated by erythropoietin; autoimmune features are also known in case of T‐LGL proliferation." (PMID 40734768, 2025). "Since PARP-1 activation is critical for sensing and recovery of DNA damage, systemic or long-term treatment with PARP-1 inhibitors may cause serious side effects, like teratogenicity and anaemia.Thus, spatiotemporal or conditional inhibition would be preferred in clinical interests." (PMID 38172953, 2024). "The most common Grade ≥3 toxicities attributed to the class effects of these drugs include anemia and fatigue, but there are distinct safety and toxicity profiles among the different PARPi that could be, in part, explained by the different trapping potency on PARP1 enzyme." (PMID 32471250, 2020).
cardiomyopathy (7 papers, 2014 to 2024). A disease of the heart muscle or myocardium proper. "This investigation provides compelling evidence that USP36 deubiquitinates PARP1, suggesting that the USP36/PARP1 axis is a promising therapeutic target for Dox-induced cardiomyopathy." (PMID 38785979, 2024). "Calcitriol is a potential PARP1 inhibitor in diabetic nephropathy and cardiomyopathy models as well as macrophage cell lines, which allows the observation of a possible relationship between vitamin D and PARP1." (PMID 34393753, 2021). "Our results provide an explanation for the cellular studies that show PARP1 activity inhibitors are detrimental to mtDNA while PARP1 depletion was beneficial in various models of cardiomyopathy, and how PARP1 could be beneficial and detrimental to mtBER." (PMID 33482196, 2021). "In summary, these results provide a deeper understanding of the regulatory role of PARP-1 in diabetic heart inflammation and apoptosis, indicating that PARP-1 inhibition may be a feasible strategy for treating diabetic heart injury and cardiomyopathy." (PMID 27027354, 2016). "The T. cruzi infection leads to ROS formation in the mitochondria, triggering PARP-1 and NF-kappaB activation, culminating in the production of pro-inflammatory cytokines such as Il-12 and IFN-γ, involved in cardiomyopathy pathophysiology." (PMID 35967878, 2022).
emphysema (7 papers, 2013 to 2023). "In vivo experiments demonstrated that PARP-1 inhibition protects against emphysema and elastase induced-inflammation and in vitro experiments showed that PARP-1 is activated upon cigarette smoke and oxidative stress." (PMID 32509795, 2020). "We used the keywords, “Cigarette smoke, COPD and PARP-1,” “PARP-1 and COPD,” “Emphysema and PARP-1,” and “Elastase induced emphysema and PARP-1” and searched Pub Med and scholarly Google articles." (PMID 28974953, 2017). "Moreover, we observed lower XLF, 53BP1, DNA ligase III, DNA ligase IV and PARP1 expression in ATII cells in emphysema in comparison with control smokers." (PMID 30696938, 2019). "Others have shown that treatment with olaparib (PARP1 inhibitor) ameliorated MMP2 and MMP9 expression in an elastase-induced mouse model of emphysema." (PMID 33172999, 2020). "Interestingly, poly (ADP-ribose) polymerase-1 (PARP-1) has also been shown to play a significant role in elastase-induced lung inflammation and emphysema in a mouse model of COPD." (PMID 33187221, 2020). "However, in a study using a model of elastase-induced emphysema and chronic lung inflammation in mice, prolonged inhibition of PARP1/ARTD1 with olaparib reduced the number of macrophages in the bronco-alveolar lavage after 21 days of treatment when compared with the control group." (PMID 37513811, 2023).
injury (7 papers, 2013 to 2025). Damage inflicted on the body as the direct or indirect result of an external force, with or without disruption of structural continuity. "As recent studies suggest, inhibiting PARP-1 in models of CNS injury, including traumatic brain injury and spinal cord injury, has demonstrated therapeutic promise by mitigating cellular damage and promoting tissue preservation." (PMID 40370754, 2025). "Activation of PARP-1 has been observed to facilitate the expression of Ca2+ permeable channels and to alter mitochondrial Ca2+ homeostasis in ischemic or traumatic brain injury, and in a NMDA toxicity model in rat primary cortical neurons." (PMID 37924373, 2023). "And our findings were similar to previous reports where PARP-1 up-regulation was found to promote differentiation of Th17 cells and suppress differentiation of Treg cells in LPS-induced lung injury." (PMID 35190759, 2022). "More importantly, PARP-1 activation is uncovered to promote the expression level of IL-6 in LPS-induced acute lung injury, which promotes the differentiation of Th17 cells and reduces the differentiation of Treg cells." (PMID 35190759, 2022). "A recent study has shown that activated PARP-1 upregulates the expression level of IL-6 in LPS-induced acute lung injury, which promotes the differentiation of T helper 17 (Th17) cells and represses the differentiation of CD4+CD25+Foxp3+ regulatory T (Treg) cells." (PMID 35190759, 2022). "Although the functions of PARP1 in the processes of myelination and remyelination remain elusive, PARP1 can limit axonal regrowth, indicating that inhibition of PARP may possess therapeutic values and boost neurological recovery after CNS trauma." (PMID 36438061, 2022).